INSIG2 (insulin induced gene 2)
Diseases named in the same sentence as INSIG2 in open-access papers (continued):
Sharing a sentence is not in itself a finding about the gene and the disease.
childhood asthma (2 papers, 2012 to 2013). "Of the 27 combinations of three-way gene-gene interaction, GSTP1 GG, IL4Ra GA and INSIG2 GG resulted in the highest risk for childhood asthma." (PMID 22355322, 2012). "Moreover, the IL4Ra and INSIG2 gene combination interacted with GSTP1, STAT6, ADRB2, ADRB3, IL13 and EPHX1 exon 3 to reveal a high training-balanced accuracy above 58.38% in childhood asthma." (PMID 22355322, 2012).
colorectal cancer (2 papers, 2020 to 2021). A primary or metastatic malignant neoplasm that affects the colon or rectum. "The expression of INSIG2 has been associated with the progression of colorectal cancer metastasis and its outcome." (PMID 33586351, 2021). "On the contrary, INSIG2 has been found to be overexpressed in colorectal cancer tissue where it contributes to poor survival and promotes malignant behaviour as cellular proliferation, invasion, and anchorage-independent growth increased while apoptosis reduced." (PMID 32577155, 2020).
coronary artery disease (2 papers, 2010 to 2014). "A study of coronary heart disease (CHD) in Chinese individuals reported that INSIG1 and INSIG2 had gene-gene interaction on risk of CHD occurrence." (PMID 25028659, 2014). "The goal of this study was to determine the relationship between the INSIG2 rs7566605 SNP and multiple cardiovascular phenotypes in a well-characterized population of patients with known coronary artery disease." (PMID 20920244, 2010).
Hypertension (2 papers, 2009 to 2014). The presence of chronic increased pressure in the systemic arterial system. "On the other hand, INSIG2 may be associated with maternal hypertensive disorders, and the presence of these disorders makes the mothers less likely to breastfeed." (PMID 20354568, 2009).
cognitive decline (1 paper, 2020). "Overall, the INSIG-2 rs7566605 SNP may be associated with cognitive decline." (PMID 32596317, 2020). "In the present study, we aim to investigate the potential protective role of CC genotype of INSIG-2 in cognitive decline." (PMID 32596317, 2020).
Cognitive impairment (1 paper, 2020). Abnormal cognition is characterized by deficits in thinking, reasoning, or remembering. "So, we hypothesize that INSIG-2 plays an important role in cognitive impairment via regulating cholesterol homeostasis." (PMID 32596317, 2020).
endometriosis (1 paper, 2025). The growth of functional endometrial tissue in anatomic sites outside the uterine body. "This study employed an integrated multi-omics approach to identify and validate five core molecules (SRPRB, RBM3, INSIG2, GYG1, and FBXW2) demonstrating significant differential expression in both endometriosis and RIF, with robust diagnostic discriminatory power." (PMID 41462508, 2025). "Western blot analysis consistently demonstrated that the protein expression levels of SRPRB, RBM3, INSIG2, GYG1, and FBXW2 were significantly reduced in both endometriosis and RIF groups compared to the normal group, with statistical analysis validating these findings." (PMID 41462508, 2025).
Hyperinsulinemia (1 paper, 2016). An increased concentration of insulin in the blood. "The differentially expressed Srebf1 and Insig2 between CON, WD and FOH groups suggest that high fat feeding induced de novo lipogenesis mainly attributed to highly Srebf1 expression in rats but not hyperinsulinemia induced SREBP1c mature, and the process was rescued by fish oil feeding." (PMID 26832365, 2016).
hypertriglyceridemia (1 paper, 2021). A laboratory test result indicating elevated triglyceride concentration in the blood. "In contrast, in this study, we found that the protective effect of INSIG2 rs11123469 (T/C) was associated with hypertriglyceridemia." (PMID 34683084, 2021). "There was a borderline significant association between the INSIG2 rs11123469 (T/C) polymorphism and hypertriglyceridemia (odds ratio = 0.54, 95% confidence interval = 0.27–1.06, p = 0.07)." (PMID 34683084, 2021). "Patients carrying the C allele of INSIG2 rs11123469 were at a lower risk for hypertriglyceridemia after controlling for potential confounders." (PMID 34683084, 2021). "Nonetheless, the SREBF2 rs2267443 (G/A) A-allele carriers were at a higher risk for hypertriglyceridemia, whereas the INSIG2 rs11123469 (T/C) C-allele carriers had a lower risk for hypertriglyceridemia, after being adjusted for clinical characteristics using multiple logistic regression." (PMID 34683084, 2021). "Moreover, the multivariate model revealed that the polymorphism of INSIG2 rs11123469 (T/C) was found to be significantly associated with hypertriglyceridemia after adjustment for the multivariate analyses (odds ratio = 0.37, 95% confidence interval = 0.14–0.97, p = 0.043)." (PMID 34683084, 2021). "Indeed, in our population, individuals with hypertriglyceridemia more often carried the common alleles (T allele) of INSIG2 rs11123469 (T/C), whereas those without hypertriglyceridemia more often carried the minor alleles (C allele)." (PMID 34683084, 2021).
psychotic disorder (1 paper, 2021). An abnormal condition of the mind that involves a loss of contact with reality. "A total of 113 patients with psychotic disorders were genotyped for the SREBF2 gene and the INSIG2 polymorphisms." (PMID 34683084, 2021).
vitamin D deficiency (1 paper, 2020). A nutritional condition produced by a deficiency of VITAMIN D in the diet, insufficient production of vitamin D in the skin, inadequate absorption of vitamin D from the diet, or abnormal conversion of vitamin D to its bioactive metabolites. "Vitamin D deficiency could raise hepatic cholesterol biosynthesis that is involved in the reduction of transcriptional activity of VDR, downregulation of insulin-induced gene-2 (INSIG2) expression and alteration of INSIG-2/SREBP-2 pathway." (PMID 32326217, 2020).
tumor (4 papers, 2021 to 2026). "In AK versus normal skin, five SMGs were significantly downregulated in at least two datasets (KIF24, KCNK5, EPB41L, INSIG2, and ABI3BP), suggesting a tumor suppressor role." (PMID 33482222, 2021). "In addition, the expression levels of AKT pS473, PCK1 pS90, INSIG1 pS207/INSIG2 pS151, and nuclear SREBP1 are higher in 451 analyzed human NSCLC specimens than in their adjacent normal tissues and positively correlated with each other in the tumor specimens." (PMID 33842305, 2021). "Consequently, this treatment abrogates PCK1‐mediated phosphorylation of Insig1 at S207 and Insig2 at S151, reduces the nuclear accumulation of SREBP1, and decreases SREBP1 activity‐dependent expression of lipid synthesis genes, lipid accumulation, and tumor cell proliferation." (PMID 40959854, 2025).
cardiovascular disease (3 papers, 2010 to 2024). "We sought to determine the relationship of the INSIG2 SNP to cardiovascular disease (CVD) related phenotypes." (PMID 20920244, 2010).
cancer (2 papers, 2021 to 2024). A tumor composed of atypical neoplastic, often pleomorphic cells that invade other tissues. "Gain- and loss-of-function studies further revealed that the INSIG2 gene product is involved in cancer migration, invasion, and maintenance of the mesenchymal phenotype in vitro, and metastasis in vivo." (PMID 39861074, 2024).
liver (1 paper, 2023). "Insig2 has a protective function in liver IR by upregulating the PPP activity and remodeling glucose metabolism." (PMID 37858181, 2023). "In summary, our investigation revealed that hepatocyte Insig2 is a protective factor against liver IR injury by optimizing glucose metabolism via the PPP, thus strengthening the antioxidant defenses and enhancing redox homeostasis of hepatocytes." (PMID 37858181, 2023). "Additionally, our research revealed that Insig2 functioned as a protecting modulator against liver IR injury, as evidenced by both in vitro and in vivo studies." (PMID 37858181, 2023).
INSIG2 also shares sentences with these, for which no sentence is quoted: atherosclerosis (2 papers); colon cancer (2); metabolic disorders (2); cerebrovascular disease (1); Cirrhosis (1); glioma (1); intestinal tumor (1).